SNU13 (small nuclear ribonucleoprotein 13)
Description:
Part of the small subunit (SSU) processome, first precursor of the small eukaryotic ribosomal subunit. During the assembly of the SSU processome in the nucleolus, many ribosome biogenesis factors, an RNA chaperone and ribosomal proteins associate with the nascent pre-rRNA and work in concert to generate RNA folding, modifications, rearrangements and cleavage as well as targeted degradation of pre-ribosomal RNA by the RNA exosome. Involved in pre-mRNA splicing as component of the spliceosome. Binds to the 5'-stem-loop of U4 snRNA and thereby contributes to spliceosome assembly. The protein undergoes a conformational change upon RNA-binding. Core component of box C/D small nucleolar ribonucleoprotein (snoRNP) complexes that function in methylation of multiple sites on ribosomal RNAs (rRNAs) and messenger RNAs (mRNAs).
Synonyms: NHP2L1; FA-1; SPAG12; SNRNP15-5; 15.5K; FA1; NHPX; OTK27; SSFA1
Tractability: Small molecule: a structure with a bound ligand is known. PROTAC: ubiquitination databases record sites on it; its protein half-life has been measured.
Gene: Protein-coding gene on chromosome 22 (41,673,933 to 41,690,504, reverse strand). Ensembl gene ENSG00000100138.
Subcellular location: Nucleus; Nucleus, nucleolus
Pathways (Reactome):
Metabolism of RNA: Major pathway of rRNA processing in the nucleolus and cytosol; mRNA Splicing - Major Pathway; rRNA modification in the nucleus and cytosol
Gene Ontology:
Molecular function: ATPase binding; box C/D sno(s)RNA binding; protein binding; RNA binding; snoRNA binding; U3 snoRNA binding; U4 snRNA binding; U4atac snRNA binding
Biological process: mRNA splicing, via spliceosome; ribosomal small subunit biogenesis; maturation of SSU-rRNA; mRNA modification; neuron differentiation; rRNA 2'-O-methylation; spliceosomal complex assembly; spliceosomal snRNP assembly; spliceosomal tri-snRNP complex assembly; spliceosome conformational change to release U4 (or U4atac) and U1 (or U11); box C/D snoRNP assembly; ribosome biogenesis
Cellular component: box C/D methylation guide snoRNP complex; dense fibrillar component; nucleolus; nucleus; precatalytic spliceosome; protein-containing complex; small-subunit processome; spliceosomal complex; U12-type precatalytic spliceosome; U2-type precatalytic spliceosome; U4/U6 x U5 tri-snRNP complex; U4atac snRNP; nucleoplasm; U4 snRNP; U4/U6 snRNP; U4atac/U6atac snRNP; U4atac/U6atac x U5 tri-snRNP complex; ribonucleoprotein complex
Genetic constraint (gnomAD): Loss-of-function variants: 2 observed, 12.78 expected, observed/expected ratio (o/e) 0.16, 90% interval 0.063 to 0.49. The upper end of that interval is the gene's LOEUF score, 0.49, which puts it in group 2 of 6, group 1 being the genes least tolerant of losing a copy. Missense variants: 66 observed, 165.42 expected, observed/expected ratio (o/e) 0.4, 90% interval 0.33 to 0.49. Synonymous variants: 68 observed, 68.96 expected, observed/expected ratio (o/e) 0.99, 90% interval 0.81 to 1.21.
Homologues: Orthologues: chimpanzee SNU13 (100% identical), dog SNU13 (100% identical), guinea pig SNU13 (100% identical), macaque SNU13 (100% identical), mouse Snu13 (100% identical), rabbit SNU13 (100% identical), rat Snu13-ps5 (100% identical), tropical clawed frog snu13 (92% identical), zebrafish snu13b (91% identical), zebrafish snu13a (90% identical), Drosophila melanogaster hoip (78% identical), Caenorhabditis elegans snu-13 (77% identical).
Diseases named in the same sentence as SNU13 in open-access papers:
SNU13 is named in the same sentence as 7 diseases in open-access papers, as found by Europe PMC text mining. Sharing a sentence is not in itself a finding about the gene and the disease. The quoted sentences say what the papers report.
breast carcinoma (4 papers, 2021 to 2025). "Published studies that queried publicly available data related to metastatic breast cancer patients revealed SNU13 as a metastasis-associated gene." (PMID 40846689, 2025).
cancer (6 papers, 2017 to 2024). A tumor composed of atypical neoplastic, often pleomorphic cells that invade other tissues. "We confirmed that various spliceosomal proteins (TIA1, SFSF4, SYNCRIP, and SNU13) can be secreted from dying cancer cells and transferred into recipient cells using GFP- and RFP- fusion constructs and subsequent confocal microscopy and western blotting." (PMID 38898005, 2024). "Conversely, knockdown of SYNCRIP or SNU13 significantly sensitized cancer cells to cisplatin." (PMID 38898005, 2024). "Furthermore, the presence of SRSF4-RFP, SYNCRIP-GFP, and SNU13-GFP in extracellular vesicles was confirmed through flow cytometry analysis of CD9 positive extracellular vesicles from dying cancer cells." (PMID 38898005, 2024).
tumor (4 papers, 2020 to 2025). "Thus, SNU13 and SYNCRIP spliceosomal proteins promote therapy resistance, while the exogenous U12 and U6atac snRNAs stimulate tumor growth." (PMID 38898005, 2024).
SNU13 also shares sentences with these, for which no sentence is quoted: acute myeloid leukemia (1 paper); asthma (1); infection (1); rectal cancer (1).